CXCR4 (C-X-C motif chemokine receptor 4)
Diseases named in the same sentence as CXCR4 in open-access papers (continued):
Sharing a sentence is not in itself a finding about the gene and the disease.
tumor (continued). "Preclinical trials confirmed the drugs that anti-CXCR4 inhibitors had anti-tumor activity against HER2 subtype of breast cancer." (PMID 35388021, 2022). "They found significantly higher CXCR4 expression in high grade tumours compared to low grade tumours and the significant suppression of apoptosis." (PMID 36140541, 2022). "Regarding the prognostic implication of CXCR4, the literature agrees that high CXCR4 expression in CRC patients is unfavorable, as it correlates with advanced tumor stage and increased risk of recurrence and distant metastasis." (PMID 35406582, 2022). "To conclude, this study demonstrated CXCR4 is significantly related to metastasis, tumor stage, tumor primary site, and overall survival in OS." (PMID 36816176, 2022). "In vitro and preclinical in vivo studies of this axis with rosiglitazone, known to inhibit the downstream signaling of CXCR4, caused the increased expression of CXCL12 in the tumor cells and decreased invasion." (PMID 36358665, 2022). "CXCR4 is a chemokine receptor overexpressed in EC tumor cells both at mRNA and protein levels, showing mostly membrane staining in cancer tissues of EC patients, which has been reported to promote metastases in our previous work." (PMID 36612081, 2022). "Of note, ex vivo work-up revealed a large variety of solid cancers and hematological malignancies, which upregulate CXCR4 on the tumor cell surface, thereby rendering this G-protein coupled receptor as an attractive target for imaging and treatment." (PMID 35674738, 2022). "CXCL12 and CXCR4 are independent prognostic factors for tumor differentiation, metastasis, and CRC survival." (PMID 35615089, 2022). "The overexpression of CXCR4 contributes to tumor growth, invasion, angiogenesis, metastasis, relapse, and drug resistance and is associated with an overall poor prognosis." (PMID 36145541, 2022). "CXCR4 blockade promotes CD8+ effector T cell tumor infiltration and is synergistic with PD-1 inhibitors in PDAC mouse models." (PMID 35774848, 2022). "Treatment with T22-PE24-H6 and T22-DITOX-H6 nanotoxins clearly impaired tumor growth in the CXCR4-overexpressing subcutaneous tumors, as tumors from the buffer-treated animals reached bigger volumes compared to their nanotoxin-treated counterparts." (PMID 35120582, 2022). "CXCR4, CXCL12, and CXCR7 are overexpressed in NETs and are associated with a higher tumor grade and advanced tumor stage." (PMID 36551599, 2022). "AMD3100 is a CXCR4 inhibitor with the potential to reverse tumor immunosuppression and has been utilized in clinic (NCT02179970, NCT01225419)." (PMID 36324128, 2022). "Treatment with AMD3100 (plerixafor), a CXCR4 antagonist, attenuates tumor growth after co-injection of tumor cells from KPC mice and PSCs." (PMID 35159011, 2022). "We predict that the emergence of anti-tumor T cell clones promoted by the CXCR4/CXCL12 axis should synergize with current immunotherapies, which remove the brakes of T cells once they recognize the antigen." (PMID 35565443, 2022). "Herein, we report an optimized radiopharmaceutical, [68Ga]Ga-BL31, with improved tumor-to-kidney contrast ratios, with superior imaging capabilities as compared to the leading clinical CXCR4-targeting radiotracer, [68Ga]Ga-Pentixafor." (PMID 35890397, 2022). "The autocrine CXCR4/CXCL12 pathway is known to activate MSCs into tumor-promoting CAFs29,43 and subsequently increases survival, migration, and cytokine secretion through PI3K/AKT signaling." (PMID 34971821, 2022). "Tumor/fibroblast interaction has been involved the progression of cancer, the CXCR4/CXCL12 chemokine axis being a main leader of malignancy." (PMID 35406582, 2022). "Previous studies have shown that CXCL12 wraps tumor cells through binding to CXCR4 and thereby prevents effector T cells from contacting cancer cells and consequently leads to immune escape/immunosuppression activities." (PMID 35681617, 2022).
tumor (continued). "The CXCL12/CXCR4 axis mediates the directional migration of CXCR4-positive tumor cells to CXCL12-expressing organs such as LNs and the liver." (PMID 35877436, 2022). "The inhibition of other TAM-recruiting chemokines such as CCL2 and CXCR4 resulted in decreased tumor growth and progression in preclinical trials; however, their performances in combination with ICIs have not yet been evaluated." (PMID 35345849, 2022). "Beyond being a key factor for tumor growth and metastasis in human cancer, C-X-C motif chemokine receptor 4 (CXCR4) is also highly expressed by a number of immune cells, allowing for non-invasive read-out of inflammatory activity." (PMID 35966583, 2022). "As an important chemokine receptor, CXCR4 is reported that it can regulate tumor cell migration, invasion, and cytoskeleton rearrangements through activating RhoA." (PMID 36552718, 2022). "As a control, the in vivo performance of 68Ga-yG5-RGD was studied in MX-1 tumor-bearing mice with a low expression of CXCR4 and integrin αvβ3." (PMID 36145541, 2022). "The combined inhibition of HER2 and CXCR4 resulted in a further reduction in primary tumor development, demonstrating A. Paniculata’s enhanced anti-tumor and anti-metastatic properties." (PMID 35682652, 2022). "It has been shown that the inhibition of CXCL12/CXCR4 signaling pathway, in combination with radiotherapy, decreased myeloid cells' infiltration; delayed tumor progression and ultimately led to anti-glioma immunological memory." (PMID 36186781, 2022). "CXCR4 is overexpressed in multiple cancer types and contributes to tumor growth, invasion, migration, metastasis, relapse, and therapy resistance." (PMID 36118530, 2022). "We observed a selective killing of CXCR4+ EC cells by apoptosis induction in cultured cells as well as in tumor models, which inhibit tumor growth and increase mouse survival after repeated intravenous doses." (PMID 36612081, 2022). "Radiotherapy, the backbone of the standard of care for gliomas, has the unintended effect of promoting tumor recurrence via CXCR4/CXCR7-dependent vasculogenesis (discussed under ‘Angiogenesis and vasculogenesis inhibitors’)." (PMID 36568151, 2022). "For this, we covalently attached hydrophobic molecules (including the antitumoral drug Monomethyl Auristatin E) to a protein targeting a tumoral cell surface marker abundant in several human neoplasias, namely the cytokine receptor CXCR4." (PMID 35057088, 2022). "CXCL12 is released from stromal cells within the TME and thus binds to CXCR4 on the surface of tumor cells, eventually promoting tumor metastases and unfavorable survival outcomes." (PMID 35795038, 2022). "In cancer, the CXCL12/CXCR4 biological axis can stimulate the proliferation and metastasis of tumor cells, regulate the inflammatory state of tumors, and activate the immune response within tumors by both autocrine and paracrine factors." (PMID 35893797, 2022). "Induction of CXCL12, CXCR4 and IDO1 in tumours have been associated with accumulation of myeloid derived suppressor cells." (PMID 35355992, 2022). "Studies further exhibited that chemokine/receptor pairs like CXCL12/CXCR4/CXCR7, CXCL16/CXCR6, and CX3CL1/CX3CR1 were obviously associated with tumor progression." (PMID 35419058, 2022). "The tumor volume of mice in the CXCR4-Kd#2/OVCA420 group treated with PTX was markedly reduced at days 13, 16 and 19 compared with mice in the Scramble-Kd/OVCA420 group treated with PTX." (PMID 35681259, 2022). "AMD3100, a CXCR4 antagonist, prevented the polarization of TAMs toward an immunosuppressive phenotype after the administration of sorafenib, which inhibited tumor growth and reduced the lung metastases in mice models." (PMID 35585567, 2022).
tumor (continued). "In that study, 68.5% of tumours showed CXCR4 expression, and of the 45 patients who developed distant metastasis, 33 (73%) had positive expression of CXCR4." (PMID 36140541, 2022). "TICs have shown a strong relation to CXCR4 in PC, with high expressing tumor cells shown to be resistant to chemotherapy treatments, such as gemcitabine." (PMID 35259193, 2022). "In this study, we aimed to identify a potential tumor sink effect in a cohort of patients with solid tumors who underwent CXCR4-directed [68Ga]Ga-PentixaFor PET." (PMID 35312939, 2022). "Favourable DMFS also pertained to higher fraction of circulating CD3+CD8+ cells positive for CXCR4 (mean of 81.5%, SD 11.4%), a chemokine receptor that promotes their infiltration into tumour sites." (PMID 34961902, 2022). "In patients, CXCR4 expression is a poor predictor of survival and a high predictor of tumor relapse." (PMID 35311145, 2022). "The CXCL12/CXCR4 axis governs TAMs’ migration into hypoxic tumor areas through the endothelial barrier." (PMID 36303138, 2022). "It is reported that the expression of CXCR4/CXCL12 is increased due to the hypoxic tumor environment, which is HIF-lα dependent." (PMID 36551144, 2022). "The pharmacokinetics and CXCR4-targeted active tumor uptake of PAMAM dendrimers can be improved through optimization of size and surface properties." (PMID 35336029, 2022). "Binding to CXCR4 turns these cells into carcinoma-associated fibroblasts (CAFs), which start to secrete CXCL12, which, in turn, acts on CSCs and tumor cells, further enhancing proliferation and/or the metastatic potential towards novel sites." (PMID 36293358, 2022). "RON knockdown suppressed BC tumor growth in xenograft mouse tumors, accompanied by reduced expression of CXCR4." (PMID 36103228, 2022). "The injection of these CXCR4-modified CAR T cells resulted in complete remission of human AML cells in peripheral blood diminishing tumor burden." (PMID 36186781, 2022). "In the next section, we focus on the role of the CXCL12/CXCR4 axis in the tumor microenvironment (TME)." (PMID 35893797, 2022). "CXCR4 is upregulated on various cancer cells, rendering this receptor as a potential target for tumor read-out and treatment strategies." (PMID 35674738, 2022). "As a result, CXCR4 and other chemokine receptors that promote tumor survival have increasingly become important targets for anticancer therapies." (PMID 36923305, 2022). "The findings suggested that CXCR4 is involved in tumor immunity of GC, and CXCR4 is considered as a potential prognostic biomarker and immunotherapy target of GC." (PMID 35388021, 2022). "Accumulated evidence indicated the critical roles of the CXCL12 − CXCR4 axis in tumor proliferation, progression, vascularization, and migration as well as the formation of an immunosuppressive TME by the exclusion of immunoreactive cells like T-cells." (PMID 35812726, 2022). "If tumour cells escape the inhibition of the CXCR‐4 antagonist, it still sensitizes the tumour cell, which renders it more receptive to therapies that can impact on tumour cell metastasis." (PMID 36398426, 2022). "In tumor–stromal cell interactions, CXCR4 and CXCL12 form an important signaling axis, with the interaction influencing adhesion, migration and invasion, reflecting the strong association of CXCR4 with the development of metastasis." (PMID 35406582, 2022). "Recent evidence shows that therapies targeting CXCR4 can increase the chemosensitivity of the tumour as well as inhibit tumour metastasis and aggressiveness." (PMID 36140541, 2022). "PYK2 modulates key signaling pathways mediated by CCL2/CCR2, CXCR4, and IL‐4Rα/pSTAT6, and positively regulates macrophage recruitment and polarization, tumor angiogenesis, and tumor growth." (PMID 35092356, 2022). "The contribution of CXCR4 in tumor cell migration involves several cellular aspects that all converge toward the facilitation of cell migration and invasion." (PMID 35406582, 2022).
tumor (continued). "Having identified the importance of CXCR4 in the recruitment of myeloid cells to the tumor, the expression of CXCR4 in CAMLs becomes of high interest to study." (PMID 35259193, 2022). "CXCR4 has also been shown to mediate different pro-metastatic events in tumor cells in vivo, such as invasion, migration, and extravasation." (PMID 36149322, 2022). "Seven days of continuous AMD3100 infusion resulted in successful CXCR4 inhibition and decreases in surrogate markers of tumor burden such as circulating tumor DNA (ctDNA) and IL-8." (PMID 36077755, 2022). "The previous studies have reported that CXCR4 promotes tumor progression by activating the PI3K/Akt/mTOR pathway in several types of cancer." (PMID 35681259, 2022). "Different downstream pathways, such as the mitogen-activated protein kinases (MAPK) cascades, convey CXCL12 signal via CXCR4/ACKR3 with roles in tumor biology." (PMID 36233192, 2022). "The plasticity of CXCR4 in forming homo- and/or heterodimers is particularly evident in tumor microenvironments where cells are exposed to multiple ligands and inhibitors, enhancing intracellular signaling." (PMID 36293358, 2022). "In the light of the significant role, CXCR4 plays in angiogenesis, and it would have been interesting to correlate the degree of CXCR4 expression on blood vessels with our molecular tumor markers." (PMID 33550492, 2022). "C-X-C motif chemokine receptor 4 (CXCR4), belongs to the C-X-C chemokine receptor family, which can promote the invasion and migration of tumor cells." (PMID 35388021, 2022). "The increase in CXCL12 and CXCR4 expression observed by us confirms the important role of the CXCL12/CXCR4 pathway in tumor development and metastasis." (PMID 36012171, 2022). "CXCR4 performs important functions in regulating tumor growth, proliferation, metastasis, autophagy, and immune responses in cancers." (PMID 36173625, 2022). "Conversely, 50% of G2 and 80% of G3 NET patients demonstrated 68Ga-Pentixafor-positive tumour lesions, which is in keeping with higher CXCR4 expression in more aggressive higher grade tumours." (PMID 36140541, 2022). "In fact, CXCR4 can be considered as a “tumour driver” which regulates the microenvironment and the dissemination of metastasis." (PMID 35325412, 2022). "CXCL12/CXCR4 axis is another molecular target for cancer treatment as this axis leads to an immunosuppressive tumor microenvironment." (PMID 35638450, 2022). "Second, the degree of expression of CXCR4 was scored for tumor cells instead of each tissue component individually, i.e., blood vessels, cytoplasm, and tumor cell nuclei." (PMID 33550492, 2022). "CXCR4 expression on the primary tumour was an independent prognostic factor and correlated with the response to first-line chemotherapy in metastatic CRC patients." (PMID 36140541, 2022). "The binding of the canonical CXCR4 ligand CXCL12 (SDF1) promotes tumour cell proliferation, survival, and metastasis, with the CXCR4+ tumour cells having a high self-renewal capacity and potent tumorigencity." (PMID 35205725, 2022). "Remarkably, although the vast majority of the cancer cells within the primary tumor were CXCR4−, when observing the tumor margin, several single cells and cell clusters that expressed CXCR4 invading the stromal tissue of the tumor edge were detected." (PMID 35456719, 2022). "Though both RON and CXCR4 overexpression has been detected in BC and their expression levels are correlated with tumor size, histological grade, and clinical stage, the relationship between RON and CXCR4 is largely unclear." (PMID 36103228, 2022). "CXCR4, a receptor of CXCL12, was also positively correlated with MT1X and is associated with tumor cell angiogenesis and proliferation." (PMID 36149322, 2022). "Comparable to the TMA analysis, all patients showed large intra-tumor variation for CXCR4 staining, even within one section." (PMID 33550492, 2022).
tumor (continued). "CXCR4 was highly overexpressed in 91.6% of tumor tissue, as compared to the level displayed by healthy cells in endometrial tissue." (PMID 35884987, 2022). "Senescent tumor cells inhibit CD8+ T cell infiltration by secreting a high concentration of CXCL12, which induces a loss of CXCR4 in T cells that result in impaired directional migration." (PMID 33643790, 2021). "CXCR4 has been found in MF cells and tumor-infiltrating lymphocytes, but reports on its expression levels in conjunction with distinct disease stages have been contradictory." (PMID 34583709, 2021). "In this study we report, for the first time, non-invasive US imaging of CXCR4 expression in the tumor vasculature using a CXCR4-targeted contrast agent, T140-MB." (PMID 34793563, 2021). "The interaction of SDF-1α and CXCR4 plays an important role in different aspects of tumour progression—including cell proliferation, survival and chemotaxis —as well as establishing metastasis in particular tissues." (PMID 33919589, 2021). "It has been shown that tumor-derived angiopoietin-like protein 2 increases CXCR4 expression on tumor cells, thus increasing their responsiveness to CXCL12." (PMID 34064859, 2021). "Ulocuplumab inhibits the binding of CXCR4 to CXCL12, and has shown both in vitro as well as in vivo anti-tumor in a WM tumor xenograft model engrafted with CXCR4WHIM mutated tumor cells." (PMID 33273682, 2021). "The current therapeutic focus is on disrupting the interaction of MM cells with their protective tumor microenvironment, in which the CXCR4 axis plays an essential role." (PMID 33668794, 2021). "To evaluate T140-MB’s ability to image receptor expression in vivo, we used two tumor models with reported differential expression of CXCR4, U2932 (high) and SuDHL8 (low)." (PMID 34793563, 2021). "Dynamic PET imaging studies using 23 were performed in mice bearing U87·CD4 or U87·CD4·CXCR4 tumor cells." (PMID 34500609, 2021). "The results demonstrate that downregulation of phosphorylation AKT/mTOR is required for Salmonella-mediated CXCR4 expression in tumor cells." (PMID 34220311, 2021). "The advanced lung patients showed an increase in LDNs expressing the CD66b+/CD10low/CXCR4+/PD-L1inter signature, suggesting an increase in the senescent neutrophil population that exhibits tumor-promoting activities." (PMID 34572138, 2021). "An active CXCL12/CXCR4 pathway is considered a feature of aggressive tumors as it positively correlates with tumor size, grading, tumor recurrence, poor prognosis and patient survival." (PMID 33937018, 2021). "Consistently, the xenograft tumor-bearing mice models were established, and the results supported that knock-down of CXCR4 inhibited tumor growth and the expression levels of Ki67 protein in vivo." (PMID 34180759, 2021). "Tao and his colleagues reported that effector B cells directly killed tumor cells via the Fas/FasL and CXCR4/CXCL12 pathways, and the killing activities can be improved by IL-2 and inhibited by IL-10." (PMID 34118931, 2021). "Blockade of CXCR4 led to an increased accumulation of T cells in a PDAC tumor model which synergized with blockade of PD-L1." (PMID 34203869, 2021). "A hypoxic tumor microenvironment favors up-regulation of CXCR4 and CXCL12 in monocytes, monocyte-derived macrophages, tumor-associated macrophages, endothelial cells, and cancer cells through a global regulator hypoxia-inducible factor-1 alpha (HIF-1α)." (PMID 34298991, 2021). "SDF-1 and one of its receptors, CXCR4, have been shown to play a crucial role in the tumor-stromal communication affecting cancer growth, angiogenesis, and metastasis formation." (PMID 33436863, 2021). "Expression of the tumor cell homing marker CXCR4 varies between different tumor areas and between cell lines." (PMID 33467498, 2021). "Blocking CXCR4 hindered BMDCs from migrating to the tumor after a single dose or fractionated doses of irradiation, thus leading to tumor volume reduction by inhibiting tumor vascularization." (PMID 34203660, 2021).